CDH1 (cadherin 1)
Diseases named in the same sentence as CDH1 in open-access papers (continued):
Sharing a sentence is not in itself a finding about the gene and the disease.
gastroenteritis (1 paper, 2019). An inflammatory disorder that affects the upper and lower gastrointestinal tract. "One possible explanation is that CDH1 mutation carriers may have a degree of innate resistance to infection with Listeria monocytogenes, a food-born pathogen that can cause gastroenteritis, meningitis, and miscarriage in pregnant women." (PMID 29589180, 2019).
gestational diabetes mellitus (1 paper, 2025). "Additionally, gestational diabetes mellitus may be linked to excessive CTNNB1 activation, which interferes with placental metabolic function and downregulates CDH1, thus disrupting placental barrier function." (PMID 40150405, 2025).
goblet cell adenocarcinomas (1 paper, 2023). "Loss of CDH1 gene function leads to gastric, breast, colorectal, thyroid, and ovarian cancer, and its mutations have been reported in appendiceal goblet cell adenocarcinomas and, very rarely, in mucinous adenocarcinomas of the appendix." (PMID 37509254, 2023).
HCMV infection (1 paper, 2012). "Therefore, virus-induced, Cdh1 phosphorylation-mediated APC regulation appears intact even without pUL21a during HCMV infection." (PMID 22792066, 2012).
Hypoglycemia (1 paper, 2021). A decreased concentration of glucose in the blood. "CDH1 levels were higher in T2D at BL, at hypoglycemia and in the initial post-hypoglycemic phase until 2-h when levels decreased significantly in T2D, thereafter reverting to BL; in controls, CDH1 levels remained steady throughout the experimental timecourse." (PMID 34926573, 2021). "CDH1 levels were higher in T2D at BL, at hypoglycemia and up to 2-h posthypoglycemia, thereafter reverting to BL levels." (PMID 34926573, 2021). "CDH1 was reported to be downregulated in AIS; however, here, its levels remained higher in T2D at all timepoints, perhaps reflecting inflammation, with a marked decrease at 2-h that may have been due to the impact of hypoglycemia on the BBB." (PMID 34926573, 2021).
intracranial meningioma (1 paper, 2021). A meningioma that arises within the cranial cavity. "Our samples of intracranial meningioma showed that, if the CDH1 gene has a genetic change, it is very likely that the CDH2 gene will also be altered." (PMID 33915799, 2021). "In a total sample of 72 intracranial meningioma, both markers for CDH1 proved to be highly informative." (PMID 33915799, 2021).
linitis plastica (1 paper, 2022). "The diffuse type is characterized by the development of linitis plastica and is associated with an unfavorable prognosis due to a heritable loss-of-function mutation of the E-cadherin gene CDH1." (PMID 35269560, 2022).
neuropathies (1 paper, 2023). "According to the immune infiltration analysis of hub genes, Cdh1 mainly correlates with plasmacytoid dendritic cells and macrophages, which can modulate the function of nociceptor sensory neurons and the development of neuropathies." (PMID 37623249, 2023).
non-small cell lung adenocarcinoma (1 paper, 2022). Type of epithelial lung cancer arising from glandular origin. "Upregulation of Cadherin-1 (CDH1), as an inhibitor of lung cell metastasis, reduces Wnt/β-Catenin activity in non-small-cell lung adenocarcinoma cells." (PMID 36147796, 2022).
otitis media (1 paper, 2021). Inflammation of the anatomical structures of the middle ear, which is most often caused by an infectious process. "By comparing the putative genes associated with congenital deafness and otitis media, only one shared gene CDH1 (ENSG00000039068) was identified." (PMID 34912812, 2021). "Specifically, CDH1 has been reported to be associated with congenital deafness due to the pathogenic alteration of inner ear but not middle ear, which has totally different pathogenic regions comparing with otitis media." (PMID 34912812, 2021).
overactive bladder (1 paper, 2022). Symptom of overactive detrusor muscle of the urinary bladder that contracts with abnormally high frequency and urgency. "In contrast, aged Cdh1+/- mice displayed a significant increase in the number of non-voiding contractions during the storage phase, indicative of an overactive bladder condition." (PMID 35361739, 2022).
Peters anomaly (1 paper, 2025). Peters anomaly (PA) is a congenital corneal opacity disorder characterized by a central corneal leukoma that obstructs the pupil leading to visual loss as well as absence of the posterior corneal stroma and Descemet membrane. "In conjunction with CDH1 and CDH3, it controls separation of the lens vesicle from the surface ectoderm during anterior segment development; thus, its association with Peters anomaly is unsurprising." (PMID 41011222, 2025).
placenta percreta (1 paper, 2023). "Several research papers support the relationship between the loss of CDH1 and placenta accreta or placenta percreta." (PMID 37174083, 2023).
placental disorders (1 paper, 2025). "Abnormal expression of CTNNB1 and CDH1 was linked to pregnancy-related placental disorders." (PMID 40150405, 2025).
RASopathy (1 paper, 2019). Developmental syndromes caused by germline mutations (or in rare cases by somatic mosaicism) in genes that alter the Ras subfamily and mitogen-activated protein kinases that control signal transduction. "We evaluated the functional criteria (PS3/BS3) of six VCEPs (CDH1, Hearing Loss, Inherited Cardiomyopathy-MYH7, PAH, PTEN, RASopathy)." (PMID 31783775, 2019).
Salmonella Infections (1 paper, 2024). Infections with bacteria of the genus SALMONELLA. "Interestingly, in the context of persistent Salmonella infection, we showed that tnfa-negative macrophages down-regulated the expression of several tight junction-related genes during persistence, such as cdh1 and tjp1a." (PMID 38224094, 2024).
sarcoidosis (1 paper, 2020). Sarcoidosis is a multisystemic disorder of unknown cause characterized by the formation of immune granulomas in involved organs. "Increased expression of TREM-2 may be involved in macrophage fusion and granuloma formation by an increase in expression of mediators of macrophage fusion, such as DC-STAMP and cadherin-1 similar to sarcoidosis." (PMID 32508528, 2020).
sarcopenia (1 paper, 2020). Progressive decline in muscle mass due to aging which results in decreased functional capacity of muscles. "We observed that the expression of IL1B, BAK1 and SOD1 were significantly increased, while the expression of CDH1, GNG11 and ZAP70 were dramatically decreased in sarcopenia samples compared to those in the controls." (PMID 32226296, 2020).
Situs inversus totalis (1 paper, 2021). "A rare case was demonstrated whereby a prophylactic laparoscopic total gastrectomy was performed in a 29-year-old male with a CDH1 gene mutation in the context of rare anatomical anomaly, situs inversus totalis (SIT)." (PMID 34025963, 2021).
skin aging (1 paper, 2021). The gradual irreversible changes in structure of skin that occur as a result of the passage of time.. "TF AR downregulated not only target gene TYR through triggering TF MITF to promote melanin synthesis, but also target gene CDH1, which was modified by phosphorylation, to promote cell-cycle, apoptosis and DNA damage in both middle-aged and elderly skin aging." (PMID 34073305, 2021).
vitamin A deficiency (1 paper, 2024). Deficiency of vitamin A due to malnutrition, malabsorption, or dietary lack. "Indeed, there was an EMT switch: Cdh1 decreased in the lungs after vitamin A deficiency (VAD) whilst Cdh2 levels increased statistically." (PMID 38674868, 2024).
ZIKV infection (1 paper, 2023). "We further performed IF staining for CGB and CDH1 in the STBTS differentiated from mock- and ZIKV-infected hTSCs, revealing reduced CGB protein after ZIKV infection." (PMID 37684223, 2023).
tumor (6,547 papers, 1993 to 2026). "CDH1 functions as a tumor suppressor, and the loss of CDH1 plays a central role in tumor metastasis." (PMID 41459333, 2026). "Downregulation of E-cadherin, often caused by transcriptional repression of CDH1, disrupts cell adhesion and polarity, and is associated with tumour progression." (PMID 41562704, 2026). "The most frequent cause is loss-of-function mutations in the CDH1 tumor suppression gene, which encodes the cell-cell adhesion protein, E-cadherin." (PMID 39760880, 2025). "CDH1 was significantly associated with tumor diameter, and patients with CDH1 mutations had larger tumor diameters." (PMID 39870503, 2025). "CDH1 (E-cadherin) is a tumor suppressor gene that encodes a calcium-dependent cell-cell adhesion glycoprotein." (PMID 40757085, 2025). "CDH1 encodes the cell adhesion protein E-cadherin, which is a tumor suppressor, and its alterations have been linked to the development of specific epithelial tumors." (PMID 40725030, 2025). "Accurate detection methods that distinguish tumor-specific from stromal methylation are needed to clarify the role of epigenetics in CDH1 loss." (PMID 40757085, 2025). "Typically, CDH1 (E-cadherin) is dysregulated in cancers, with its downregulation often associated with increased tumor invasiveness and metastasis." (PMID 40226617, 2025). "Loss of CDH1 function, primarily through truncating or missense mutations and loss of heterozygosity, disrupts cell adhesion and polarity, promoting tumor invasiveness and metastasis." (PMID 40757085, 2025). "Recent research has also focused on combining targeted therapies with immunomodulatory agents to overcome tumor microenvironment immunosuppression in CDH1-deficient cancers." (PMID 40757085, 2025). "Genomic CDH1 alterations with loss of E‐cadherin expression are observed in several tumour types such as lobular mammary, plasmacytoid urothelial, and diffuse gastric carcinoma, and result in pathological morphologies similar to single‐cell GP5 PCa." (PMID 39428716, 2025). "Previous studies have shown that EOGC is frequently associated with diffuse-type histology, CDH1 gene mutations, poor tumor differentiation, and advanced stage disease at diagnosis." (PMID 40862832, 2025). "The CDH1 encodes the calcium-dependent cell adhesion protein E-cadherin, which plays a major role in cell adhesion and tumor suppression." (PMID 41378303, 2025). "Numerous studies have shown that promoter hypermethylation (e.g., of GATA4, RASSF1A, CDH1) is closely associated with tumor suppressor gene silencing, tumor progression, and poor prognosis." (PMID 41438986, 2025). "The loss of CDH1, a tumor suppressor gene encoding E-cadherin, has been linked to the development of various cancers and increased invasiveness and tumor progression." (PMID 40725576, 2025). "In brief, ILC are primarily identified by a “single-file” pattern of tumor cell infiltration, associated with hallmark loss of cell adhesion factor E-cadherin (CDH1), distinguishing it from IDC where gland formation is present." (PMID 40640157, 2025). "For cell adhesion and metastasis, hypermethylation and loss of expression of cadherin 1 (CDH1) are closely associated with tumor invasion, metastasis, and poor prognosis." (PMID 40718833, 2025). "E-cadherin, encoded by the CDH1 gene, is a traditional tumor suppressor that upholds epithelial integrity by promoting robust calcium-dependent cell–cell adhesion." (PMID 41514650, 2025). "While the loss of CDH1 has been shown to promote tumor invasion and metastasis, especially in ER-positive breast cancer, AKT is known to stimulate tumor cell growth and proliferation by possessing anti-apoptotic properties." (PMID 40001874, 2025).
tumor (continued). "Another gene of potential interest is E-cadherin (CDH1), a transmembrane glycoprotein regulating cell-to-cell adhesion, which has been linked to tumor progression and metastasis in cases of decreased expression." (PMID 40724877, 2025). "The expression level of CDH1 can significantly influence tumor progression and metastasis, as it is associated with the abnormal activation of neuroactive ligand–receptor signaling pathways." (PMID 40331986, 2025). "Remarkably, DNMT1 is thought to be a cause of TNBC by hypermethylating the promoters of ER, several oncosuppressors, and EMT-related target genes (including CDH1, encoding for E-cadherin), thus promoting tumor growth, autophagy, and metastasis." (PMID 40141248, 2025). "CDH1 is thought to act as a tumour‐suppressor gene with the loss of gene function contributing to cancer progression by increasing proliferation, invasion, and metastasis." (PMID 40998421, 2025). "LOH occurs when one allele of the CDH1 gene is lost in a tumor cell, resulting in the loss of functional E-cadherin." (PMID 40585607, 2025). "The incomplete penetrance and the phenotypic consequences of pathogenic CDH1 mutations create significant challenges for genetic counseling and tumor prevention." (PMID 39596675, 2024). "In vitro studies of molecular events associated with AKAP9 gene expression alteration in tumour cells linked it to the action of proteins such as CDH1, Cdc42 interacting protein 4, and the Wnt/β-Catenin signalling pathway." (PMID 38203733, 2024). "Specifically, CtBPs are involved in modulating genes implicated in tumor suppression and cell cycle progression, such as E-cadherin (also known as cadherin 1, CDH1), cyclin-dependent kinase inhibitor 1 A (CDKN1A), and CDKN2A." (PMID 38902802, 2024). "CDH1 is a tumor-repressor gene that encodes E-cadherin, and its mutations are well-recognized as risk factors for GC." (PMID 38502852, 2024). "ILC is the second most commonly observed tumour in patients with CDH1 germline mutations, a mutation more commonly associated with hereditary diffuse gastric cancers." (PMID 38754140, 2024). "E-cadherin gene (CDH1) mutations are considered to be noteworthy contributors to tumor migration and invasion." (PMID 39009979, 2024). "MORC3 deficiency downregulated the E-cadherin (CDH1) tumor suppressive gene and the keratin 14 (KRT14) epithelial differential marker but significantly upregulated the expression of oncogenic JUN, CCND1, CCND2, and CCN1 at the transcriptional level." (PMID 39329063, 2024). "The CDH1 gene is a tumor suppressor that encodes E-cadherin, a transmembrane protein involved in adherens junctions of epithelial cells." (PMID 39057027, 2024). "Data from tumor genomic testing were obtained for 12 of the 15 CDH1 germline variant carriers (80.0%)." (PMID 38652475, 2024). "It is generally characterized by tumor cells that have lost their connectivity, and its unique histological appearance results from the inactivation of E-cadherin, encoded by the CDH1 gene." (PMID 39201647, 2024). "A previous study found that the loss of CDH1 expression induces oncogenic cell transformation and facilitates tumor development." (PMID 37834295, 2023).
tumor (continued). "Loss of E-cadherin, a key feature of this tumor type is due to CDH1 mutation, which occurs simultaneously with heterozygous deletion in chromosome 16q in majority of the cases." (PMID 38001750, 2023). "CDH1 encodes E‐cadherin and has been reported to act as a tumour suppressor and to be downregulated in GC." (PMID 37118990, 2023). "The homophilic transmembrane protein E-cadherin, which is localized to adherens junctions in epithelial tissue and plays a tumor suppressor role, is encoded by the CDH1 gene." (PMID 38132192, 2023). "Using a genetic approach to assess E-cadherin/Cdh1 function in the aberrant Snail expression model, we knocked out one floxed allele of the Cdh1 tumour suppressor in Pdx1-Cre;KrasG12D/+;SnailKI/+ mice." (PMID 36882420, 2023). "CDH1, a tumor suppressor gene that encodes E-cadherin, mediates cell-to-cell adhesion between neighboring cells." (PMID 36810560, 2023). "We have discussed potential mechanisms underlying the observed expression changes in CDH1 and E-cad during tumor progression." (PMID 37189027, 2023). "Among genes obtained from the Nichenet algorithm that specifically upregulated in C cells, CDH1 would act as a tumor suppressor gene encoding a classical cadherin." (PMID 37744240, 2023). "In contrast to the textbook knowledge of the loss of E-cad during tumor progression and metastasis, the levels of CDH1 mRNA and E-cad protein are either upregulated or remain unchanged in most carcinoma cells compared to normal cells." (PMID 37189027, 2023). "Reassuringly, E-cadherin (encoded by the EMT-gene CDH1) was found significantly down-regulated in tumor vs. normal tissue, a prototype marker for EMT." (PMID 37170215, 2023). "The primary tumour for case number 4 contained an exon 8 mutation in CDH1 whereas in metastasis this gene was wild-type." (PMID 37670299, 2023). "On the contrary, levels of Cldn1,Cldn4,Cldn6,Cldn9,Cgn,F11r, and Cdh1, associated with exacerbated inflammation, perturbation of the TJ assembly, and even with mesenchymal transformation or tumour progression, were overexpressed." (PMID 37794493, 2023). "In histopathologic analysis, ILC is most often characterized by infiltrating, poorly cohesive tumor cells with poor expression of E-cadherin, a cell adhesion protein encoded by the CDH1 gene." (PMID 37758801, 2023). "Co-administration of the FAK inhibitor IN10018 enhances the anti-tumor effect of ROS1 inhibitors in the treatment of CDH1-deficient cancers." (PMID 37324948, 2023). "While the loss of cell adhesion, e.g., due to mutations of CDH1, is a hallmark of certain cancers, tissue-specific cadherin expression is useful to distinguish between different cell types and determine tumor progeny." (PMID 36010583, 2022). "Somatic mutations in CDH1 have been associated with the epithelial–mesenchymal transition in tumor cells, resulting in a more aggressive tumor phenotype." (PMID 36232418, 2022). "CDH1, a tumor suppresor gene which encodes E-cadherin, was reactivated commonly in 5-aza-dC and TSA treatment in RKO cells." (PMID 36077707, 2022). "They showed that miR-9 targets the transcripts of CDH1 gene encoding E-cadherin and enhances the activity and nuclear localization of β-catenin which are both involved in tumor angiogenesis." (PMID 35499045, 2022). "Lobular BC is driven by mutational inactivation of CDH1/E-cadherin and is a slow-growing tumor entity." (PMID 35842479, 2022). "The five CDH1 mutant (CDH1MT) tumours also showed concomitant LOH of CDH1 and copy number loss of the remaining allele." (PMID 35053458, 2022). "Of the nine tumours studied here, four of these harboured clonal mutations in CDH1 in both the Neg and Ab components." (PMID 35053458, 2022). "Of the four CDH1 wild-type (CDH1WT) tumours, two (ML6 and ML12) showed differential copy number loss of the CDH1 locus at 16q22.1 with the Neg component showing a copy number loss of CDH1 and the Abr component retaining both alleles." (PMID 35053458, 2022).